MAPK10 (mitogen-activated protein kinase 10)
Diseases named in the same sentence as MAPK10 in open-access papers (continued):
Sharing a sentence is not in itself a finding about the gene and the disease.
cancer (continued). "In addition, our results showed that the upregulation of miR-335-5p inhibits the expression of MAPK10 in MKN-28/SGC-7901 cancer cells at the RNA and protein levels." (PMID 33482821, 2021). "We previously discovered that MAPK10/JNK3 is a novel broad TSG for multiple cancers." (PMID 32089740, 2020). "Notably, we also found that one of the genes in our list, MAPK10 is silenced in several types of cancer." (PMID 23391219, 2013). "The possible molecular mechanism involved in cancer pathways, PI3K-Akt signaling pathway and viral carcinogenesis pathway via the inhibition of CASP3, MMP3, SRC, MAPK10 and CDK6 and the activation of PPARα and JAK." (PMID 38675723, 2024). "The possible molecular mechanism involves inhibiting cleaved CASP3, MMP3, SRC, MAPK10 and CDK6, and activating PPARα and JAK, which are typically involved in cancer pathways, the PI3K-Akt signaling pathway and viral carcinogenesis pathways." (PMID 38675723, 2024). "There are 42 intersecting targets of cancer/tumor with PKVG phenolic acid-based active ingredients, and the top four DC were MAPK1, EGFR, MAPK10, and PRKCA by network analysis." (PMID 39689118, 2024). "The degree of methylation of PIK3R5, PIK3R1, MAPK10, and CD40 genes in cancer tissues was significantly increased compared to normal tissue, while most of the remaining genes were reduced." (PMID 37666853, 2023). "MAPK10, a member of the MAPK family, plays a key role in cancer initiation and progression by acting as an integration point for multiple biochemical signals." (PMID 36185996, 2022). "Mitogen-activated protein kinase 10 (MAPK10, also known as JNK3) is a member of the MAP kinase (MAPK) family, and MAPKs play a crucial role in the carcinogenesis and cancer progression by acting as the integration point for multiple biochemical signals." (PMID 34408980, 2021). "The role of MAPK10 and STAT4 in cancer cell necroptosis has been unidentified." (PMID 37095524, 2023). "MAPK10, FOS, and IL-6 genes show extensive low expression in LUSC, BRAC, KICH, and other cancers." (PMID 37666853, 2023). "We thus propose that MAPK10 and ICAM1 are potential prognostic factors and targets for therapy in HCC, warranting further research of connections between these molecules, immune response and cancer cell survival." (PMID 34408980, 2021). "Specifically, for the MAPK10 gene, which has 192 known transcripts, our analysis revealed that only 24 transcripts showed significant correlations with metrics such as TSM, TMB, or MSI across 17 cancer types, appearing in up to 47 different signature identifiers." (PMID 41048343, 2025). "Noteworthy in this regard is the involvement of JNK3 (MAPK10) in these signaling events and has been verified by our JNK3 protein kinase inhibition experiment showing that the repression of the JNK3 expression is essential for the enhancement of PTX toxicity in cancer cells." (PMID 23409748, 2013).
tumor (34 papers, 2013 to 2025). "Several studies have shown that abnormal activation or inhibition of MAPK10 signaling is associated with tumor cell proliferation, invasion and metastasis." (PMID 40725119, 2025). "Frequent loss of Mapk10 expression has been detected in a panel of tumor cell lines, together with the proapoptotic functions observed, suggesting its potential role as a TSG." (PMID 33604188, 2021). "Small HCC usually implies a better clinical outcome, and Cox hazards models based on GEPIA indicated that CD6 and MAPK10 were tumor suppressors associated with a good clinical prognosis, which was consistent with the results of our study." (PMID 33225985, 2020). "We found that high MAPK10 expression associates with increased transcriptional signatures of tumor infiltration lymphocytes (TILs), suggesting that MAPK10 could be implicated in the recruitment of TILs into the TME of HCC." (PMID 34408980, 2021). "The distinct roles of MAPK10 isoforms in tumor progression and interactions with the microenvironment also emphasize the need for targeted therapeutic approaches." (PMID 41048343, 2025). "We further validated the impact of MAPK10 on tumor immune infiltration using C57/BL6J mice, which usually used as the model for immune microenvironment analysis." (PMID 38360860, 2024). "Multivariate analysis confirmed that tumor localization and ARAF and MAPK10 mutations were independent predictive factors of reduced DFS (HR = 2.1; 95% CI: 1.1–4.0; p = 0.019; HR = 3.9; 95% CI: 1.2–13.1; p = 0.027; HR = 49; 95% CI: 9.8–244.1; p < 0.001)." (PMID 37835512, 2023). "Univariate analysis revealed that tumor localization in the right colon and ARAF and MAPK10 mutations were associated with reduced DFS." (PMID 37835512, 2023). "When the expression of MAPK10 is low, the infiltration of M2-type macrophages is more substantial, suggesting that MAPK10 is a tumor suppressor gene." (PMID 34579753, 2021). "We utilized the bioinformatics predictions and computer simulations followed by in vitro functional assays to characterize the putative role of MAPK10 in HCC tumor microenvironment." (PMID 34408980, 2021). "Further steps indicated that the ectopic expression of Mapk10 in silenced HCC cells significantly inhibited the tumor cell growth or induced the apoptosis." (PMID 33604188, 2021). "To explore the mechanism of the tumor suppression by Mapk10, we performed apoptosis assay using Annexin V-PE and 7-AAD double staining." (PMID 33604188, 2021). "The frequent silencing of Mapk10 by hypermethylation in HCC cell lines rendered Mapk10 as a putative tumor suppressor." (PMID 33604188, 2021). "Conversely, Mapk10 hypermethylation was reduced in paired non-tumor tissues, suggesting a role of Mapk10 as a candidate TSG in the pathogenesis of HCC." (PMID 33604188, 2021). "In summary, Mapk10 is functions as a tumor suppressor and frequently inactivated by promoter methylation in HCC." (PMID 33604188, 2021). "In the present study, we found that the expression of Mapk10 is frequently silenced or downregulated in most of the paraffin-embedded HCC tissues (63%) when compared with the adjacent non-tumor tissues." (PMID 33604188, 2021). "We found that the mean value of MAPK10 mRNA expression in surrounding non-tumor tissue of HCC was 0.115694 (FPKM)." (PMID 34408980, 2021). "The heat map displayed that when the expression of MAPK10 is low, the purity of the tumor is lower, the immune score is higher, the stromal cell score is higher, and the expression of eight immune-associated genes is higher." (PMID 34579753, 2021). "MAPK10, a member of the Jun N-terminal kinase subgroup of mitogen-activated protein kinases, has proapoptotic functions and can function as a tumor-suppressor protein to suppress tumorigenesis." (PMID 31159150, 2019). "Among the 130 up-regulated genes, those encoding E-cadherin, MAPK10, MAP3K5, and PAK3 have been confirmed to inhibit tumor proliferation or invasion." (PMID 28454092, 2017).
tumor (continued). "Both the histology and staging data from GSE:6008 and Nature 2011, respectively, showed that MAPK10 was decreased in expression compared to normal which was consistent as its established role is as a tumor suppressor." (PMID 24423449, 2014). "Although increased CD8+ T-cell infiltration was associated with improved survival in our cohort, the concomitant overexpression of CCL18 and epigenetic silencing of MAPK10 indicate a complex interplay between tumor-intrinsic alterations and the immune microenvironment." (PMID 41472741, 2025). "Intriguingly, the expression of MAPK10 in HCC patients was negatively correlated with the scores of tumor cells, illustrating that MAPK10 might exert anti-tumor effects in HCC (correlation coefficient R = −0.43." (PMID 34408980, 2021). "Consistently, signals such as MAPK10, which promote the continuous infiltration of immune cells into tumor microenvironment, may improve the prognosis of HCC patients in clinical immunotherapeutic treatment." (PMID 34408980, 2021). "Moreover, considering the critical role of tumor progression in the overall survival of patients with GC, the prognostic value of these hub genes was assessed; MAPK10 was significantly correlated with patients’ overall survival." (PMID 33558567, 2021). "Finally, the clinical correlation analysis found that the silenced expression of Mapk10 in HCC was dramatically correlative with the advanced tumor stage and poor prognosis of HCC patients." (PMID 33604188, 2021). "Mapk10 (JNK3) was shown to be silenced or downregulated in a majority of the HCC cell lines or primary HCC tumor samples examined, while the demethylating reagent could restore its expression in silenced HCC cells." (PMID 33604188, 2021). "Group-specific distal enhancers or SEs could control TSGs such as DLC1 and MAPK10 directly or indirectly via group-specific core regulators, which might help to explain the downregulation of these TSGs and tumor progression in GII." (PMID 34001209, 2021). "Moreover, the expression of multiple immune genes strongly correlated with MAPK10 expression in the tumor microenvironment." (PMID 34408980, 2021). "The direct upregulation of MAPK10/JNK3 expression and activation of downstream proapoptotic targets may be an important mechanism of the tumor suppression of ZNF471 in ESCC cells." (PMID 32089740, 2020). "Because our previous data indicated that MAPK10 expression might modulate the immune activity in the tumor microenvironment though the recruitment of TILs or TAMs into the TME, we attempted to understand the precise molecular mechanism of this proposed process." (PMID 34408980, 2021). "Concomitantly, the expression of ICAM1 in MAPK10-deficient Huh7-shMAPK10 cell line was significantly lower than in the control Huh7-pLKO cell line, suggesting that the silencing of MAPK10 leads to reduced expression of ICAM1 in HCC tumor cell context (P = 0.0401)." (PMID 34408980, 2021). "Many of these genes, including those encoding bFGF, MAPK10, MAP3K5, IL1R2, E-cadherin, Ki67, Cyclin E1, beta-catenin, 14-3-3 protein T-cell (YWHAQ), integrin alpha-V (ITGAV), integrin alpha-10 (ITGA10), CDK6, PCNA, CDKN1A, and PAK3, are related to tumor metastasis and regulation of cell migration." (PMID 28454092, 2017). "For example, MAPK10 isoforms showed distinct phenotypic correlations, while COL1A1 and UMOD displayed gene-level coordination in regulating tumor stemness." (PMID 41048343, 2025). "MAPK10 is a member of the JNK subgroup in the MAPK superfamily and has been proposed as an epigenetically inactive tumor suppressor." (PMID 38675723, 2024). "Mitogen-activated protein kinase 10 (Mapk10) is a member of the c-jun N-terminal kinases (jnk) subgroup in the MAPK superfamily, and was proposed as a tumor suppressor inactivated epigenetically." (PMID 33604188, 2021).
tumor (continued). "HCC patients with low MAPK10 expression have lower expression scores of tumor infiltration lymphocytes (TILs) and stromal cells in the TME and increased scores of tumor cells than those with high MAPK10 expression." (PMID 34408980, 2021). "The suppressive role of ZNF471 in ESCC is mediated through the regulation of various tumor suppressors, such as MAPK10/JNK3 and protocadherin (PCDH) genes that are involved in apoptosis induction and cell adhesion, respectively." (PMID 33672287, 2021). "Tumor cells with frequent nuclear fragmentation were primarily observed in xenografts with ZNF471 expression, along with increases in MAPK10 staining, decreases in Ki-67 staining and increases in cell apoptosis." (PMID 32089740, 2020). "PIK3CD, MAP4K1, and MAPK10, which are key members of the LPS-stimulated MAPK pathway, are highly expressed in patients with high tumor burden." (PMID 33225985, 2020). "It was also found that ERK pathway was enriched in tumor specimen after receiving chemotherapy, several ERK pathway component genes expression elevated in KEGG and REACTOME GSEA results, such as MAPK10, MAPK13, MAPK11 and MAPKAPK3." (PMID 29296238, 2017). "The clinicopathological correlation analysis showed that the negative expression of MAPK10 in HCC was significantly associated with higher serum AFP (p = 0.05), more microsatellite nodules (P = 0.025) and advanced tumor stage (P = 0.001)." (PMID 33604188, 2021). "The clinical analysis of the paraffin-embedded tissues also revealed that the negative expression of Mapk10 was significantly associated with higher serum AFP, more tumor microsatellite nodules, advanced tumor stage, and the shorter OS of HCC patients." (PMID 33604188, 2021). "The significantly regulated genes identified in both KYSE150 and KYSE410 cells were found to be involved in cell adhesion (PCDH family genes, CLDN1, CNTN1), cell apoptosis (MAPK10/JNK3, PYCARD), tumor suppression (TUSC3, SAMD9L) and immunity regulation (IFNL3)." (PMID 32089740, 2020). "Moreover, we revealed that the mRNA levels of MAPK10 in HCC tumor tissues were significantly reduced compared to non-tumor tissues (Wilcoxon test, P = 7.062 × 10-4)." (PMID 34408980, 2021). "In fresh primary tumors, the Mapk10 promoter was frequently methylated in 12/18 (66%) HCC tissues, while reduced or no methylation was detected in the adjacent non-tumor tissues, suggesting that the methylation of Mapk10 is tumor-specific." (PMID 33604188, 2021). "As for 46 paired paraffin-embedded tissues, all of the adjacent non-tumor tissues show the positive expression of MAPK10, whereas 29 HCC tissues show the negative expression, the negative expression rate of MAPK10 between the HCC and the adjacent non-tumor tissues was significant (P < 0.0001)." (PMID 33604188, 2021).
neurodegenerative disease (18 papers, 2019 to 2025). A disorder of the central nervous system characterized by gradual and progressive loss of neural tissue and neurologic function. "MAPK10 has been identified as a possible target and biomarker of neurodegenerative diseases." (PMID 33964983, 2021).
infection (10 papers, 2014 to 2025). The state of being infected such as from the introduction of a foreign agent such as serum, vaccine, antigenic substance or organism. "The mRNA levels of Mapk3 (Erk1) and Mapk10 (Jnk3) decrease upon FM1 infection but increase with XDY treatment." (PMID 39897040, 2025). "Several MAPK encoding genes, such as MAPK11, MAPK12, and MAPK13, were significantly up-regulated under HN10 infection and MAPK10 was significantly up-regulated under JDm10 infection." (PMID 35893682, 2022). "Mapk10 mRNA was downregulated after infection with FM1 on both time points, while upregulated by XDY supplementation." (PMID 32957919, 2020). "We noted that Mapk3 (Erk1) mRNA and Mapk10 (Jnk3) mRNA were reduced during FM1 infection, but enhanced with XDY treatment." (PMID 32957919, 2020). "Except for MAPK10 Y185 all phosphosites in this group returned to normal levels by 7 h post-infection." (PMID 25101063, 2014). "Components of the JNK and p38 MAPK pathway were induced upon early infection, including the c-Jun N-terminal kinase (JNK) gene MAPK10 as well as the transcription factor AP-1 components FOS, JUN and JUNB." (PMID 38427950, 2024).
MAPK10 also shares sentences with these, for which no sentence is quoted: Cerebral ischemia (13 papers); Parkinson disease (8); cognitive decline (7); Stroke (7); Anxiety (4); cervical cancer (4); neurological disorders (4); prostate carcinoma (4); ischemic stroke (3); amyloid (2); brain injury (2); cardiovascular diseases (2); cognitive disorder (2); glaucoma (2); Glucose intolerance (2); Huntington disease (2); metabolic disease (2); myocardial infarction (2); ocular hypertension (2); pancreatic cancer (2); renal cell carcinoma (2); viral infection (2); amyotrophic lateral sclerosis (1); anaplastic thyroid cancer (1); angina (1); Autoimmunity (1); B-cell lymphoma (1); basal cell carcinoma (1); bladder tumors (1); brain diseases (1).
A further 38 diseases each share a sentence with MAPK10 in 1 paper.